LIF (LIF interleukin 6 family cytokine)
Diseases named in the same sentence as LIF in open-access papers (continued):
Sharing a sentence is not in itself a finding about the gene and the disease.
tumor (continued). "However, it remains unclear whether LIF in fact drives the metastasis suppressor actions of LIFR, since most data suggest that LIF is tumor-promoting." (PMID 32023849, 2020). "LIF effects on metastasis were ablated through the shRNA knockdown of LIF in MDA-MB-231 cells, but given the absence of a functional LIFR in these cells, the effects observed in vivo would most likely be mediated through paracrine LIF signaling from the tumor cells to the microenvironment." (PMID 32023849, 2020). "The fact that both LIFR and LIF are overexpressed in NPC tumors derived from patients with metastasis implies that elevated cytoplasmic LIF in tumor cells may not originate from the microenvironment." (PMID 30504771, 2018). "A very important property of EGFRvIII-expressing tumor cells consists of their capacity to exert paracrine effects on neighbor cells through the release of microvesicles containing the mutant EGFR or mitogenic cytokines, such as interleukin-6 (IL-6) and leukemia inhibitory factor (LIF)." (PMID 30279357, 2018). "Currently, the mechanism for LIF overexpression in tumor cells is not well-understood." (PMID 25726527, 2015). "Importantly, recombinant LIF could activate STAT3 and downregulate RET and induce tumor suppression in human MTC cells xenografted in mice, suggesting its potential as a therapeutic reagent to treat MTC." (PMID 24662939, 2014). "Our studies also suggest that monitoring the status of phospho-ERK1/2 and phospho-FAK S910 in tumor biopsies can be a good indicator for adverse effects, and that blood levels of IL8 and LIF may serve as markers, because normal cells were either inhibited or not-responsive to the drug." (PMID 20149136, 2010). "Interestingly, the positive LIF effect on tumor cell viability is not dependent on Stat3 activation, which inhibits tumor cell survival as it does in normal mammary epithelium." (PMID 17925034, 2007). "Whereas previous studies have shown that targeting suppressive monocytes in PDAC with a CCR2 inhibitor could enhance chemotherapy, in our current study, inhibition of monocytes from entering the tumor with a CCR2 inhibitor did not significantly affect the chemo/anti-LIF/anti-PD-L1 response." (PMID 39857986, 2025). "Therefore, AAV directed production of CXCL9 at the tumor site, independent of LIF expression, may be applicable to a broader range of GBM patients." (PMID 38997283, 2024). "The related mechanisms may involve an inhibitory effect on the IL-6/LIF system, promoting the release of ligands of the CXCR3 receptor, chemokines CXCL9 and CXCL10 (IP-9), which chemoattract several types of immune cells that infiltrate a tumor and prevent its growth." (PMID 38891915, 2024). "However, we observed a significant induction of S100a14 suggesting that although IL-6 and LIF may contribute to tumor features, they do not directly contribute to EMT." (PMID 36828915, 2023). "Instead, extracellular components, including LIF, CCL2, PDGFA, Hippo/YAP1, as well as, immune responses and angiogenesis, might pivotally participate in development of intratumor heterogeneity through remodeling methylome and transcriptome of tumor foci from same mGBM patients." (PMID 34987659, 2022). "Likewise, when we explored the effects of IL1β-silenced tumor cells on co-cultured NCFs, we could observe that cocultured fibroblasts lost the expression of inflammatory cytokines, as IL6, LIF or CCL2, while acquired markers of myofibroblasts (ACTA2, PDPN, MYH11, or CNN1)." (PMID 34066976, 2021). "In addition, knockdown of LIF but not IL-6 impaired tumor initiation rate in xenograft models." (PMID 31296870, 2019). "Additionally, cRGDfC treatment of static mESCs in the presence or absence of LIF was able to inhibit tumor formation upon transplantation of mESCs into mice, suggesting that the interaction of the mESCs within ECM molecules in vivo is at least partly required for tumorigenesis." (PMID 29137597, 2017).
tumor (continued). "However, CDSF includes LIF and insulin, and failed to support the tumor-like growth of mESCs." (PMID 21731714, 2011). "A key discovery was a substantial increase in the secretion of LIF (leukemia inhibitory factor) and HGF (hepatocyte growth factor) in heterotypic spheroids with CAFs (BrC4f), irrespective of the molecular type of tumor cells." (PMID 41597220, 2026). "LIF levels were markedly elevated in the C26 tumor milieu, whereas other known wasting factors (IL-6, TNF-α, myostatin) were not, indicating that LIF is the key wasting cytokine in this model." (PMID 40869331, 2025). "LIF was actively secreted by C26 tumor cells, whereas TNF-α and IL-6 were not, and incubation of C2C12 myotubes with LIF was sufficient to induce atrophy." (PMID 33329046, 2020). "The results showed that the expression of SH2D2A and GATA2 were upregulated (P = .0067 and P = .6021, respectively), while CXCL8, LIF, and VASH2 were downregulated in IVL tumor samples compared to nontumor tissue (P = .9281, P = .5406 and P = .0625, respectively)." (PMID 32372565, 2020).
cancer (238 papers, 2005 to 2026). A tumor composed of atypical neoplastic, often pleomorphic cells that invade other tissues. "Multivariable analysis confirmed NBI as the strongest independent predictor of carcinoma, while epithelial LIF and LIFR expression showed inverse associations with histological malignancy and high-risk NBI vascular patterns." (PMID 41752061, 2026). "Leukemia Inhibitory Factor (LIF) is a another pleiotropic cytokine of the IL-6 family that has emerged in the last decade as a key contributor to cancer cachexia, particularly muscle loss." (PMID 40869331, 2025). "Together, these findings demonstrate that LIF produced by cancer cells acts directly on muscles to cause atrophy, primarily through JAK2/STAT3 signaling." (PMID 40869331, 2025). "The LIF/LIFR axis has been implicated in several hallmarks of cancer, including enhanced proliferation, immune evasion, chemoresistance, and poor patient survival." (PMID 41154625, 2025). "LIF secreted from cancer cells and cancer‐associated fibroblasts promotes cancer stemness by driving SOX2 transcription in an autocrine/paracrine manner, respectively." (PMID 39206755, 2024). "Analysis of cancer databases revealed that elevated expression of LIF or LIFR was associated with poor progression-free survival of OCa patients and a predictor of poor response to chemotherapy." (PMID 38789520, 2024). "The secretion of LIF from several human and mouse cancer cell lines has been associated with cancer cachexia development in mice inoculated with these cancer cells." (PMID 38245529, 2024). "The LIF/LIFR axis is linked to cancer proliferation, immune system protection, chemoresistance, and patient survival." (PMID 39518071, 2024). "We first measured the expression of genes involved in adipocyte differentiation (PPAR-γ, AP2, HSL, Adiponectin, Leptin), cancer-associated fibroblast (CAF) markers (LIF, FAP, α-SMA), and inflammation (IL-6, IL-8, IL-1β, CXCL-10, TNF-α)." (PMID 39072314, 2024). "A wide variety of cytokines, many of which have been implicated in cancer pathogenesis, are known to signal through receptors that include gp130, such as IL-6, IL-11, LIF, and OSM." (PMID 38022653, 2023). "LIF–LIFR was identified to be an important cancer-associated regulatory hub in advanced CRC and patients with higher expression of LIF in CRC tissue were associated with a lower overall survival (OS) rate." (PMID 37360193, 2023). "Further, LIF/LIFR signaling in cancer cells has been linked to several oncogenic properties, including proliferation and cell survival, playing a role in immune system and chemoresistance." (PMID 38139260, 2023). "The immunological inhibition of LIF resulted in reduced skeletal muscle loss, thus confirming LIF’s role in cancer cachexia." (PMID 36900198, 2023). "Within various cancer types, LIF expression has been linked to hallmarks of cancer, such as proliferation, metastasis, and chemoresistance, as well as overall patient survival." (PMID 35204717, 2022). "Currently, the underlying mechanisms whereby LIF promotes tumorigenesis are still not well understood, and the role of LIF in cancer metabolic reprogramming is unclear." (PMID 35440095, 2022). "To begin understanding cytokine-induced adipocyte lipolysis, we initially compared adipocyte lipolysis by the cancer cachexia-associated cytokines IL-6 and LIF to that of the well-characterized lipolytic factor and β-adrenergic agonist isoproterenol." (PMID 35785158, 2022). "Here, we set out to compare adipocyte lipolysis signaling by cancer cachexia-associated IL-6 family cytokines (IL-6 and LIF) to that of the β-adrenergic agonist isoproterenol." (PMID 35785158, 2022). "Although LIF-LIFR signaling activates a variety of pathways associated with cancer progression such as JAK/STAT and MAPK, more potent and significant activators of these pathways already exist and are potential targets for treatment." (PMID 34395259, 2021).
cancer (continued). "Neutralizing antibodies (Abs) knock down the activity or expression of LIF and reduce in vitro the stem cell-like properties of murine slow-growing CSCs (American association for cancer research, 2012)." (PMID 34295890, 2021). "In contrast to LIF typically being associated with the increased invasion and metastasis of cancer, LIFRβ expression has been shown to be correlated with the opposite." (PMID 34395259, 2021). "In cancer, LIF has been shown to activate cancer-associated fibroblasts to promote contractility, extracellular matrix remodeling, and cancer cell invasiveness." (PMID 31156640, 2019). "Recent investigations have implicated the role of JAK-STAT signaling and LIF-mediated activation of cancer-associated fibroblast (CAFs) in the deposition of desmoplasia and its associated mechanisms in multiple cancers, including PC." (PMID 30899415, 2019). "The roles of inflammatory cytokines such as IL-1, 6, TNF-α, and leukemia inhibitory factor (LIF) in causing cancer cachexia are known." (PMID 30410674, 2018). "LIF-rich cancer cells (cLIF) caused more significant damage to the HUVEC layer, which appeared unrepairable, compared to that induced by WT parental and LIF+/− cancer cells." (PMID 30504771, 2018). "This is the first study to report that LIF production is promoted by TLR5 in cancer cells as a mechanism underlying the worsening of cancer cachexia." (PMID 30410674, 2018). "From a clinical perspective, AZD0530 treatment presents an ideal strategy to disrupt the metastatic process in cancers associated with LIF, LIFR, or YAP1 activation." (PMID 30504771, 2018). "Our data collectively suggest that AZD0530 reverses the LIF-associated cancer invasive phenotype, at least partly, by increasing cytoplasmic YAP1 and suppressing expression of the focal adhesion components p-PXN and p-FAK." (PMID 30504771, 2018). "In the current study, we investigated the mechanisms underlying the LIF-mediated cancer metastasis and provide evidence linking LIF with cancer dissemination by driving invadopodia formation and modulation of the YAP1-FAK/PXN pathway." (PMID 30504771, 2018). "A recent report shows that LIF promotes proinvasive activation of carcinoma-associated stromal fibroblasts, which results in increased cancer cell invasion." (PMID 26716902, 2016). "A very recent study reported that the induction of LIF expression in cancer-associated fibroblasts can promote onset of a proinvasive microenvironment." (PMID 25726527, 2015). "The LIF (leukemia inhibitory factor)/LIFR (leukemia inhibitory factor receptor) cytokine signaling pathway has been linked to the progression of a variety of cancers; however, its importance in IBC has yet to be determined and was investigated in this study." (PMID 40075639, 2025). "However, the role of LIF in cancer cachexia and especially its underlying mechanism are far from clear." (PMID 38245529, 2024). "Taken together, our results support that progranulin, mainly derived from macrophages, and LIF, mainly derived from cancer cells, drives pSTAT3+myMAF activation, and inhibition of either progranulin or LIF is sufficient to disrupt their associated pro-metastatic functions." (PMID 38678021, 2024). "CXCL1 expression is also upregulated by LIF secreted by cancer-associated adipocytes." (PMID 37108425, 2023). "Leptin causes higher secretion level in VEGF/VEGFR2 and LIF in carcinoma than benign cells." (PMID 37600567, 2023). "As cancer is a leading cause of death, investigating potential roles of LIF to determine whether manipulation of LIF signaling could reveal novel treatment options has become increasingly important." (PMID 35204717, 2022). "LIF overexpression promotes proliferation, metastasis and chemo-resistance of cancer cells, and is associated with poor prognosis in various types of cancers." (PMID 35440095, 2022). "Cancer with positive lymph node metastasis was associated with higher LIF expression (p = 0.022)." (PMID 31973037, 2020).
cancer (continued). "Similarly, a significant association between LIF staining and advanced cancer staging (stages III and IV) (p = 0.002) was noted." (PMID 31973037, 2020). "Notably, induction of both IL-11 and LIF in response to TGF-β stimulation of cancer-associated fibroblasts is thought to promote tumor progression." (PMID 31156640, 2019). "Cancer-associated genes LIF and PAPPA are possible targets of miR-500a-3p." (PMID 28952053, 2018). "In summary, results from this study demonstrate that hypoxia induces LIF expression in human cancer cells mainly through HIF-2α, which could be an important underlying mechanism for LIF overexpression in human cancers." (PMID 25726527, 2015). "Interleukin-like EMT inducer (ILEI) is a cytokine-like protein of the FAM3C family that is speculated to have a four-helical bundle structure similar to LIF and has been implicated in a number of pathophysiological contexts, including Alzheimer’s and cancer metastasis." (PMID 34395259, 2021). "This is also supported by the experimental observations of elevated OPN and LIF levels in ICI-resistant patients in across different cancers." (PMID 40460357, 2025). "According to the proposed network, the cancer-associated fibroblasts grow through i) self-proliferation via OPN-mediated autocrine interaction and ii) LIF-induced conversion from wild-type fibroblasts." (PMID 40460357, 2025). "Proinflammatory cytokines such as leukemia inhibitory factor (LIF) and IL-6, released by both cancer cells and CAFs, contribute to the epigenetic modification of CAFs, leading to enhanced protumorigenic function by remodeling of the extracellular matrix." (PMID 40805183, 2025). "Inhibiting LIF presents a promising therapeutic approach due to its potential to affect various cancer mechanisms." (PMID 39857986, 2025). "Among these, MSC-1 (also known as AZD0171), a humanized monoclonal antibody, has shown strong and specific LIF antagonism in multiple cancer types." (PMID 39857986, 2025). "The potential of inhibiting the LIF/LIFR axis for cancer treatment has been demonstrated using neutralizing antibodies or engineered ligand traps." (PMID 40075639, 2025). "Clinically, elevated LIF expression correlates with poor prognosis and reduced responsiveness to anti-cancer treatment." (PMID 39857986, 2025). "LIF has been attributed with paradoxical roles in cancer progression, either inhibiting blood-borne leukemic cell proliferation or promoting the development of some solid tumors." (PMID 40072060, 2025). "LIF, a cytokine of the IL‐6 superfamily, plays intricate roles in cancer cell proliferation, migration, metastasis, and immune evasion, and has been widely reported in various types of cancer progression, including HCC." (PMID 40416597, 2025). "LIF/LIFR signaling has been associated with proliferation, progression, metastases, stemness, and chemoresistance in several cancers." (PMID 40075639, 2025). "In our analysis, co-culture of mouse CAFs with PC-3 or PC-42 cancer cells upregulated the secretion of mouse IL-6 and LIF from CAFs compared with monoculture of CAFs, and EBET-1055 treatment canceled the upregulation." (PMID 38467634, 2024). "Noticeably, SMAD3 serves as a key TF involved in LIF transcription in both cancer cells and CAFs via different regulatory models." (PMID 39206755, 2024). "As expected, CM media generated from HSCs stimulated with recombinant progranulin and cancer cell CM in the presence of LIF-nAb showed a significant reduction in promoting colony formation compared to IgG group." (PMID 38678021, 2024). "Collectively, our findings unveil two independent regulatory models for LIF in HNSCC cancer cells and CAFs to promote LIF transcription, respectively." (PMID 39206755, 2024). "Initially, we found the highest percentages of LIF immunohistochemistry staining in HNSCC samples as compared to other cancers using The Human Protein Atlas datasets and aberrant overexpression of LIF mRNA across multiple cancers including HNSCC." (PMID 39206755, 2024).